AFP (alpha fetoprotein)
Diseases named in the same sentence as AFP in open-access papers (continued):
Sharing a sentence is not in itself a finding about the gene and the disease.
tumor (continued). "AFP and CA19-9 emerged as key tumor markers for differentiating HCC and ICC." (PMID 40128070, 2025). "Although specific tumor markers are generally absent, one recent case reported a markedly elevated AFP level (1111.93 ng/mL)." (PMID 41293148, 2025). "Postoperatively, there was a marked decrease in serum AFP levels, and no tumor recurrence was observed over a 60-month follow-up period." (PMID 39706145, 2025). "The multivariate analysis included Child–Pugh classification, BCLC stage, type of resection, type of hepatectomy, largest tumor size, degree of oncological radicality, RBC and FFP transfusion, postoperative complications, AFP, PLR, ANRI, Fib-Alb, SII, PNI, APRI, and ALBI." (PMID 40869491, 2025). "Elevated serum levels of AFP, β-hCG, or CA 125 are strongly indicative of ovarian cancer; however, negative results do not rule out the presence of malignancy, as tumor markers are elevated in only 50% of malignant tumors." (PMID 40723200, 2025). "CBC, liver function test (LFT), renal function test (RFT), electrolytes, and tumor markers like carcinoembryonic antigen (CEA), prostate-specific antigen (PSA), alpha-fetoprotein (AFP), human chorionic gonadotropin (HCG), and lactate dehydrogenase (LDH) were all within normal biological values." (PMID 40026996, 2025). "Existing prediction models predominantly rely on preoperative factors, such as alpha-fetoprotein (AFP) levels and the tumor burden score (TBS)—a continuous variable calculated from tumor size and number—to estimate recurrence-free survival (RFS) post-hepatectomy." (PMID 40238062, 2025). "Our patient had mildly elevated liver enzymes and elevated AFP levels; however, a normal AFP level is not an uncommon finding seen in fibrolamellar or poorly differentiated tumours." (PMID 41583252, 2025). "Moreover, integrating MER with AFP, BCLC, or tumor size led to a substantial elevation in the AUCs, reaching 0.868 (95% CI: 0.756–0.979, p < 0.001), 0.931 (95% CI: 0.857–1.000, p < 0.001), or 0.920 (95% CI: 0.838–1.000, p < 0.001), respectively." (PMID 40075616, 2025). "This suggests that AFP is not merely a biomarker but also contributes significantly to the complex process of tumor formation, emphasizing the importance of targeting AFP in therapeutic approaches." (PMID 40430002, 2025). "An analysis of the diagnostic efficacy of anti-OLA1 autoantibody was conducted across different clinical subgroups, including metastasis status, tumor multiplicity, TNM stage, gender, and AFP status, due to the limited sample size in the Beijing center, data from the other two centers were used." (PMID 41246329, 2025). "However, there are rare instances where tumor markers such as CA19–9, CEA, AFP, CA47–7, and CA72–4 have tested positive." (PMID 40168880, 2025). "A significant reduction in the levels of tumor markers, including AFP and DCP, was observed, and to date, the patient has not had any detectable recurrence of HCC." (PMID 39857967, 2025). "Tumour burden at presentation was similar, but PWH had a higher proportion of advanced BCLC‐C stage (22% vs. 10%, p < 0.001), more frequent MVI and/or EHS (27% vs. 11%, p < 0.001), and elevated AFP > 200 ng/mL (28% vs. 15%, p = 0.001)." (PMID 41250947, 2025). "For instance, a randomized clinical study demonstrated that preoperative AFP levels are not linked with postoperative survival in HCC individuals, likely due to tumor stage heterogeneity." (PMID 40429981, 2025).
tumor (continued). "The MHG model = 20 × the VICT2 trait (present, 1; absent, 0) + 9 × serum AFP (> 100 ng/mL, 1; ≤ 100 ng/mL, 0) + 7 × tumor growth subtype (non-simple nodular type, 1; simple nodular type, 0)." (PMID 39702639, 2025). "OS was influenced by tumor location and AFP status in univariate analysis, though these were not independent predictors in multivariate analysis." (PMID 39958339, 2025). "Tumor markers, including CA-125 and AFP, are usually normal and therefore not clinically helpful, as seen in this case." (PMID 41552138, 2025). "Circulating tumor cell subsets expressing cancer stem cell markers (CD90, epithelial cell adhesion molecule; CD133, vimentin) were assessed using multiparametric flow cytometry and compared with alpha-fetoprotein and des-gamma-carboxy prothrombin." (PMID 40940925, 2025). "Increased AFP levels at the time of diagnosis had significant importance for non-complete treatment response, last tumor diameter, vascular invasion, increased metastasis, and mortality." (PMID 40181742, 2025). "By contrast, early changes in alpha-fetoprotein and des-gamma-carboxy prothrombin were not consistently related to tumor size, progression-free survival, or overall survival." (PMID 40940925, 2025). "Gender, age, Alpha-Fetoprotein(ATP), nonsmooth tumor margin, and maximum 2D diameter did not significantly differ between the cohorts." (PMID 40636460, 2025). "All local and metastasized tumors were completely removed in the surgical excision, with no residual tumor remaining in the post-operative tumor assessment by CT/MRI and AFP at two months." (PMID 40186764, 2025). "CA125, AFP, and CEA are commonly used clinical tumor markers." (PMID 40406247, 2025). "Other baseline characteristics, including age, sex, ECOG performance status, Child-Pugh score, ALBI score, and tumor markers (AFP, DCP), did not significantly differ among the three groups." (PMID 41019089, 2025). "Not many tumor markers are recommended for cancer screening and AFP is among them, alongside CA 125, human chorionic gonadotropin (hCG), and a few others." (PMID 40723883, 2025). "In addition, Tumor maximum diameter, ECOG PS, ALT, AFP level, and ΔsADC were also independent predictors of OS in patients." (PMID 41137952, 2025). "Tumour markers, particularly AFP and β-HCG, are critical for diagnosis, risk stratification, and monitoring of treatment response, especially in non-seminomatous tumours." (PMID 41523526, 2025). "This does not imply that AFP or tumor size were irrelevant but rather that in this specific, early-stage, and treatment-homogeneous cohort, their incremental value was limited." (PMID 40937437, 2025). "Furthermore, with the exception of AFP, β-HCG and SCC, the abnormal rates of the other tumor markers were difference between these AIDs." (PMID 40660406, 2025). "Adjunctive therapy Y90 radioembolization worked by controlling tumor size and AFP levels, facilitating the crucial aspect of liver transplantation with tumor resection with negative margins." (PMID 40755645, 2025). "The advantage remained consistent regardless of AFP level, portal vein invasion, tumor diameter, or extrahepatic metastasis." (PMID 40909949, 2025). "International guidelines recommend that CHB-infected patients should be surveilled for HCC by ultrasound with or without serum tumor biomarker alpha fetoprotein (AFP) test every 6 months." (PMID 40231168, 2025). "Our study demonstrated positive correlations between serum AFP, β-HCG, and LDH levels and hematological indices, such as neutrophil count, NLR, and PLT×NLR, supporting the hypothesis that tumor burden is accompanied by systemic inflammatory activation." (PMID 41527642, 2025). "Vascular invasion and extrahepatic disease are general exclusion criteria while total tumour volume (TTV) and alpha-fetoprotein (AFP) criteria may vary by centre." (PMID 40710208, 2025).
tumor (continued). "Tumor markers (HCG, AFP, LDH) should be requested, as well as a full body CT scan, while taking a transtesticular biopsy is not recommended, as it may guide drainage into the inguinal lymph nodes, and complicate treatment." (PMID 41567310, 2025). "Key clinical factors impacting Ki‐67 expression in HCC included alpha‐fetoprotein (AFP), non‐smooth tumor margin, ill‐defined pseudo‐capsule, and peritumoral star node." (PMID 39964132, 2025). "Notably, our study revealed a significant correlation between tumor markers (β-HCG and AFP) and the proportion of infiltrating CD4+ and Foxp3+ cells, as well as CTLA-4 expression." (PMID 39958339, 2025). "Tumor markers revealed an elevated alpha-fetoprotein (AFP) level of 74.10 ng/mL and negative carcinoembryonic antigen (CEA), carbohydrate antigen 125 (CA 125), and carbohydrate antigen 19-9 (CA 19-9) levels." (PMID 41555997, 2025). "In cases with high AFP levels, regardless of treatment regimen, tumor growth tends to be more rapid, and prognosis is generally shorter." (PMID 40447887, 2025). "A few patients may have abdominal pain, ascites, hepatomegaly, jaundice, emaciation, etc., with normal or slightly elevated blood AFP, CEA and tumor markers (CA199, CA125)." (PMID 39917171, 2025). "Tumor markers, including CA 19-9, CEA, and AFP, were all within normal limits." (PMID 41250722, 2025). "The tumor necrosis caused by TACE increased the release of tumor-associated antigens, which has been proven to recruit DCs and increase AFP-specific CD4+T-cell response, thus synergizing with ICIs to increase cytotoxic T lymphocytes and decrease tumor-infiltrating Treg cells." (PMID 40129919, 2025). "Specifically, cytoplasmic AFP activates the PI3K/Akt/mTOR signaling pathway and reduces cell autophagy, thereby playing a crucial role in cell growth, survival, proliferation, and tumor progression." (PMID 40430002, 2025). "Routine blood test results were within normal limits, anti-HIV was negative, and tumor markers (including alpha-fetoprotein/AFP, beta-human chorionic gonadotropin/ Beta HCG, lactate dehydrogenase/ LDH) were within normal limits." (PMID 38504239, 2024). "The factors influencing organoid establishment were determined by comparatively analyzing the clinical data from patients: samples with larger tumor volumes, microvascular invasion, terminal PLC stage, and high levels of AFP expression had a greater likelihood of establishing successful organoids." (PMID 39192365, 2024). "Anti-HCC T-cell immunity may be elicited via the abnormal expression of oncofetal and cancer testis antigen genes (AFP, GPC3, MAGE-1 and NYESO1), viral peptide, or tumour-specific neoantigens." (PMID 39308986, 2024). "Consistent with the high AFP abnormality in the high SERPINH1 expression group in tumors, the high SERPINH1 expression group in tumors also showed enrichment of tumor stemness pathways, along with abnormal activity in unfavorable pathways such as alternative splicing and DNA replication." (PMID 39430252, 2024). "When paired with serum AFP, SNRNP70 may also be able to predict postoperative results and the likelihood of tumor recurrence." (PMID 38500533, 2024). "Serum tumor markers (lactate dehydrogenase, human chorionic gonadotropin, and alpha-fetoprotein) can be useful to rule out germ cell testicular cancer." (PMID 39682143, 2024). "The most important timing of additional TACE is tumor progression after having shrunk once or cases in which the AFP value is elevated despite no progression on imaging evaluation." (PMID 39451736, 2024). "Therefore, many researchers propose incorporating AFP and DCP into the HCC staging system, aiming to compensate for the current system’s focus only on morphological features such as tumor diameter, number, and vascular invasion." (PMID 38903723, 2024). "Laboratory tests revealed an elevated C-reactive protein and ferritin levels, while tumor markers such as AFP, CEA, CA199, CA125, CA50, and T-SPOT were negative." (PMID 39144665, 2024).
tumor (continued). "Alpha-fetoprotein (AFP) and CA19-9 is also used to evaluate the nature of the tumor." (PMID 38704534, 2024). "We conducted a subgroup analysis focusing on PNS, which unveiled notable distinctions between patients exhibiting erythrocytosis and those without such syndromes regarding tumor size, albumin levels, and AFP levels (p < 0.001)." (PMID 38674198, 2024). "These parameters include AFP levels at the time of LT, a sum of the explants' largest viable tumor diameter number of lesions, and the presence or absence of MVI." (PMID 39749089, 2024). "The results of the univariate analysis showed that HBeAg positivity, high HBV-DNA load, tumor size, tumor differentiation, MVI, satellite lesions, capsule invasion, PT, Hb, and elevated ALT, AST, NLR, and AFP levels (> 400 ng/ml) were significant predictors of OS." (PMID 38622578, 2024). "Items utilized in this scoring system for uHCC patients undergoing Atez/Bev treatment include tumor burden, that is, BCLC, and malignancy potential, that is, AFP and DCP, the same as used for CRAFITY score, while hepatic reserve function (mALBI 1, 2a, 2b, 3) is also included." (PMID 38577725, 2024). "Across the cohort, we find negative correlations between LGR5 expression and serum AFP at the time of transplant and the tumour cell proliferative fraction by Ki67 staining." (PMID 39169164, 2024). "Diagnosing GTS can be challenging, as serum tumor markers commonly used to monitor NSGCT, such as AFP and β-hCG, may remain within normal limits." (PMID 38817478, 2024). "In an effort to predict HCC recurrence and based on the different scores based on pathological findings, the number of locoregional treatments before LT could be used as a surrogate for tumor aggressiveness and/or advanced HCC at presentation, such as AFP." (PMID 38473400, 2024). "The EASL–EORTC guidelines do not currently recommend tumor biomarkers such as AFP, AFP-L3, and DCP for routine early HCC detection, as they lack cost-effectiveness and sufficient clinical efficacy." (PMID 39682122, 2024). "For example, a 66-year-old patient with a Child-Pugh score of 6, his AFP at baseline is 792.6 ng/ml, ALB is 34.7 g/L, TBLT is 13.4μmol/L, largest tumor size is 4cm, tumor number is 2, by using our model, he got a survival rate at 1-, 3-, 5-year is 0.819, 0.519 and 0.386." (PMID 38434985, 2024). "As a result, in the respective patient subgroups of age >65 years, viral etiology, ALBI grade 1, AFP>1000 ng/mL, PIVKA-II>1000 mAU/mL, ECOG 0, Child-Pugh 5A, largest intrahepatic tumor >5 cm, multiple intrahepatic tumors, or PVI, AB had significant benefits in OS." (PMID 38482199, 2024). "A variety of studies have evaluated the correlation between SNHG1 expression and the clinicopathological characteristics of HCC patients, including tumor size, histological grade, presence of lymph node and distant metastases, disease stage (AJCC/BCLC), and AFP levels." (PMID 39200161, 2024). "Tumor markers which include CA125, lactate dehydrogenase (LDH), alpha-fetoprotein (AFP), and HCG are essential for malignancy confirmation in perimenopausal women, allowing them to be referred to a tertiary care center for early proper intervention and to decrease patient's morbidity." (PMID 39246853, 2024). "Four serum tumor biomarkers, CEA, CYFRA21-1, NSE, and AFP, were tested." (PMID 38167564, 2024). "Fourthly, our study focused exclusively on AFP without including other relevant tumor markers, such as protein induced by vitamin K absence or antagonist-II." (PMID 38433845, 2024). "Tumor number, microvascular invasion (MVI), AGPR and radiomic features were independent risk factors for early postoperative recurrence in patients with AFP-negative HCC." (PMID 38849749, 2024). "Elevated tumor markers were infrequently observed in SPN, with 5.6% showing increased levels of neuron specific enolase (NSE), followed by carcinoembryonic antigen (CEA) (2.2%), carbohydrate antigen 19-9 (CA 19-9) (1.1%), and alpha fetoprotein (AFP) (0.5%)." (PMID 38469229, 2024).
tumor (continued). "Laboratory investigation involves tumor markers such as β-HCG and AFP." (PMID 39099693, 2024). "The lack of correlation between tumor response and serum AFP levels in this case highlights a more general clinical unmet need to identify WT-specific circulating tumor markers." (PMID 38098239, 2024). "In this study, we found that TyG was significantly correlated with several well-known prognostic factors, such as AFP, tumor size, and number, but not with the TNM stage." (PMID 39537878, 2024). "Further diagnostic evaluation may include the assessment of testicular malignancies using serum tumor markers such as lactate dehydrogenase (LDH), human chorionic gonadotropin (hCG), and alpha-fetoprotein (AFP)." (PMID 39886106, 2024). "In contrast, all the tumor markers but PIVKA-II were determined to have quite low positive rates in the early stage even though they showed increased positive rates, except CEA and AFP, in the advanced stage." (PMID 39795568, 2024). "Our findings align with existing literature in suggesting that elevated mMDSCs levels are indicative of aggressive HCC phenotypes, including advanced BCLC stages, elevated serum AFP and PIVKA‐II levels, and the presence of portal vein tumor thrombus and metastases." (PMID 39222024, 2024). "AFP and CEA are commonly used tumor markers in gastrointestinal tumors." (PMID 38515458, 2024). "Furthermore, the administration of AFP-CAR T cells in NSG mice bearing Hep G2 tumors intravenously resulted in swift and significant inhibition of tumor growth." (PMID 38473878, 2024). "Currently, GC is diagnosed based on alpha-fetoprotein (AFP), cancer antigen 19-9 (CA19-9), cancer antigen 125 (CA125), carcinoembryonic antigen (CEA), and other tumor markers; however, the specificity of these markers is low, and there is a lack of effective targeted therapies." (PMID 38824174, 2024). "From the distribution of clinical characteristics of the patients, we observed that the operation being laparotomy, high preoperative AFP levels, BCLC stage of stage B, greater tumor diameter, multiple tumors with hepatic capsule invasion or the MVI, and higher TBS." (PMID 39555448, 2024). "It serves as a clinical tumor marker, function as a carcinogen, immune suppressor, and transport vehicle; but the detailed AFP structural information has not yet been reported." (PMID 38678117, 2024). "The prognosis following LEN–TACE treatment was linked to improved survival outcomes in patients with substantial tumor burden, including those with portal vein tumor thrombosis (PVTT), AFP levels of ≥400 ng/mL, three or more intrahepatic tumors, and a primary tumor size of ≥5 cm." (PMID 39062006, 2024). "Key markers such as alpha-fetoprotein (AFP) and beta-human chorionic gonadotropin (β-HCG) are frequently elevated in NSGCT and correlate with more aggressive disease, offering insights into metastatic potential and overall tumor burden." (PMID 39727674, 2024). "The performance of predictive models was evaluated using receiver‐operating characteristic curve (AUC) values, considering several single immune parameters with inter‐group differences, as well as AFP and CEA, which are commonly used tumor markers in clinical practice to assess treatment efficacy." (PMID 39467150, 2024). "The original tumors were positive for AFP and HepPar1 similarly to transplanted HepYF-M13 tumors but showed reduced Sox9 and no significant Krt19 expression in tumor cells." (PMID 39051113, 2024). "Subgroup categorizations were based on age (<60 or ≥60 years), gender, AFP levels (≤400 or >400 ng/mL), tumor size (≤2 or >2 cm), presence of multiple tumors (no or yes), and the ablation route (laparoscopic or percutaneous)." (PMID 38774215, 2024). "If there are no signs of tumor recurrence and metastasis in two consecutive imaging examinations and the tumor markers (AFP, PIVKA-II), the adjuvant therapy can be suspended." (PMID 39080533, 2024).